IL4 (interleukin 4)
Diseases named in the same sentence as IL4 in open-access papers (continued):
Sharing a sentence is not in itself a finding about the gene and the disease.
tumor (continued). "IL-33 blockade restricted SCC outgrowth, decreased Th2-derived IL-4 and increased the accumulation of Th1 IFNγ-producing cells in tumour-draining lymph nodes, and thus represents a promising SCC treatment strategy." (PMID 38662248, 2024). "To further determine the effects of IL-4 on anti-PD-1 therapy resistance, we examined the anti-tumor effects of the PD-1 antibody in xenograft 615 mice that received MFC cells." (PMID 39003253, 2024). "PGE2 also reduces the expression of cytokines, i.e., INF-γ and IL-4, shifting the immune balance towards Th2 cells; in this way, it contributes to an increase in anti-tumour activity by promoting immunosuppressive cells such as regulatory CD4+CD8+FoxP3+ Tregs." (PMID 39120301, 2024). "One of the many physiological actions of IL-4 is to negatively modulate Th1 T cells, dendritic cells, and IFNγ production, facilitating tumor growth." (PMID 38607023, 2024). "M2-like macrophages mediate the immune escape of tumor cells through PD-1 and are activated by interleukin (IL)-4, IL-10, IL-13, or colony-stimulating factor 1 (CSF-)." (PMID 39113885, 2024). "While IL-4 has been proposed to be the primary activator of pro-tumoural TAMs such as the “M2” phenotype, it also has some anti-tumour effects thought to be related to the maturation of myeloid precursor cells." (PMID 38903497, 2024). "IL-4 is reported as one of immune-suppressive cytokines in tumor microenvironment that help tumor growth and metastasis." (PMID 39502692, 2024). "The high levels of IL-4 can induce an increase in the activity of tissue proteases in macrophages, thereby promoting tumor growth, invasion, and tumor angiogenesis." (PMID 38903721, 2024). "Research shows that basophils infiltrate various human cancers and induce immune protection in the tumor microenvironment by secreting cytokines such as IL-4/IL-13 to polarize macrophages to the M2 phenotype." (PMID 38388357, 2024). "It has been proved that both IFN-γ and IL-4 can effectively upregulate the expression of PD-L2 in either immune cells or cancer cells, so we further examined the effects of both IFN-γ and IL-4 on PD-L2 secretion of tumor cells." (PMID 39511147, 2024). "This conversion of IL-4 signaling inhibition into a signal that amplifies the antitumor efficacy of CAR–T cells at the tumor site (signal 3-stimulatory cytokine signaling) serves to safeguard CAR–T cells against cytokine-mediated suppression." (PMID 39220130, 2024). "For example, HSP72 and HSP105 on the surface of tumor exosomes can promote tumor metastasis by inducing IL-4 secretion from DCs in a TLR6 and TLR2-dependent manner." (PMID 38633106, 2024). "IL-4-induced polarization of M2 macrophages can interchangeably utilize glucose or tumor-derived lactate as a TCA cycling carbon source." (PMID 39430253, 2024). "Both peripheral blood lymphocytes and tumor-infiltrating lymphocytes demonstrate a predominant polarization toward the secretion of IL-4 and other Th2 cytokines." (PMID 39452870, 2024). "Tumor cells induce autophagy in monocytes and TAMs by secreting cytokines such as M-CSF, GM-CSF, and IL-4." (PMID 39430253, 2024). "In turn, tumor cell-derived IL-4 induces the activation of CAFs and stimulates POSTN expression by activating STAT6." (PMID 38773979, 2024). "Significantly increased IL4 production was observed in the control tumor-bearing group of animals during the follow-up period." (PMID 38786612, 2024). "After treatment with PCL, there was a significant decrease in Ki-67, CD31, and VEGF levels in tumor tissues and a reduction in serum IL-4 levels in tumor-bearing mice." (PMID 39902075, 2024). "Low levels of interferon-γ and high levels of IL-4 promote macrophage differentiation into M2, facilitating tumor progression." (PMID 39020276, 2024).
tumor (continued). "In contrast, interleukins like IL-4, IL-5, IL-10, and IL-13, which contribute to the chronic inflammatory protumorigenic response, promote tumor progression and immune evasion through their interactions with the tumor microenvironment." (PMID 39456897, 2024). "Here, we describe a new mechanism by which anti-PD-1 mAb promotes antigen-specific CD8+ T cell responses by stimulating Tfh cells and IL-4 production in tumor-draining lymph nodes." (PMID 38417020, 2024). "Th2 cells stimulate M2-TAMs cathepsin protease activity in tumors by releasing IL-4, leading to enhanced tumor invasiveness and proliferation in the IL4-/-RT2 animal model and in vitro." (PMID 38509593, 2024). "For instance, Tregs can convert to Th1 or Th17 types, while Th1 cells secrete cytokines like IFN-γ and IL-2 that enhance anti-tumor immunity, and Th2 cells release IL-4 and IL-10, which can promote tumor growth." (PMID 39769334, 2024). "Immunohistochemical staining, western blot, qRT-PCR and ELISA analyses further confirmed that IL-4 was significantly down-regulated in the tumor tissues of Postn-/-Rag1-/- injected with IHH-4 cells compared to their Postn+/+Rag1-/- counterparts." (PMID 38773979, 2024). "Osteopontin promotes tumor cell proliferation, recruits macrophages, and synergizes with IL-4 to further polarize them into a pro-tumorigenic state." (PMID 39448577, 2024). "Tumor-promoted Th2 polarization can suppress T cell anti-tumor response by secreting IL-4, IL-5, and IL-10; in fact, untreated or progressive BC is associated with lower levels of IFN-γ and IL-2 and higher levels of Th2 cytokines." (PMID 39682686, 2024). "In those patients with PDAC, basophils expressing IL4 have been found in tumor-draining lymph nodes (TDLNs), and their presence emerged as an independent negative prognosis indicator for patient survival." (PMID 39816393, 2024). "Another unexpected observation was the critical role of IL-4 in mediating the effect of anti-PD-1 in the tumor-draining lymph node." (PMID 38417020, 2024). "Conversely, M2 macrophages, which play a role in tissue repair and tumor progression, are polarized by factors such as interleukin-4 (IL-4) and interleukin-13 (IL-13)." (PMID 39766056, 2024). "Nevertheless, when the tumor grows, the tumor cells repolarize to M2-type TAMs by a variety of pathways, including the production of cytokines including CSF-1, IL-4, and IL-10, lactate secretion, nutrient shortage, and hypoxia." (PMID 38185636, 2024). "IL-4 upregulates other tumor microenvironmental cytokines including IL-10 which induce immunosuppressive conditions and thus peripheral tolerance of tumor-infiltrating immune cells." (PMID 39057050, 2024). "In summary, these results indicate that IL-4 enhances the production of lactic acid by enhancing glycolysis in M2 macrophages, promotes the formation of tumor acidic microenvironment, and upregulates the expression of FcγRIIB." (PMID 39003253, 2024). "We uncover a feedback loop involving tumor cell-derived IL-4 and CAF-derived POSTN, which highlights the intricate crosstalk between tumor cells and their microenvironment." (PMID 38773979, 2024). "IL-25 production is stimulated by IL-4 and IL-13 cytokines—produced by tumor cells and Th2 cells—and periostin produced by dermal fibroblasts." (PMID 38607023, 2024). "Following differentiation, Th2 cells secrete IL-4, IL-5, IL-10, IL-13, and IL-17 and eventually undergo tumor growth and metastasis." (PMID 38238581, 2024). "Anti-tumor macrophages (M1) can polarize into pro-tumor macrophages (M2) via IL-4, IL-10, and IL-13." (PMID 39125923, 2024). "The Th1 phenotype can secrete IFN-γ, IL-2, and other factors to fight tumors, but IL-4 and IL-5 secreted by the Th2 phenotype have tumor-promoting effects." (PMID 36844875, 2023). "M2 macrophages, on the other hand, activated by IL-4, IL-10, and IL-13, promote tumor growth and suppress anti-tumor immune responses." (PMID 38201551, 2023).
tumor (continued). "Consistently, blocking IL‐5 pathway also contributes to tumor growth, while overexpressing IL‐5 or IL‐4 helps to predominantly improve eosinophils, macrophages infiltration to enhance tumor clearance." (PMID 37829505, 2023). "Next, the RAW264.7 cells were pre-treated with cytokine interleukin-4 (IL4) to induce the M2 phenotype to simulate the macrophages at the tumor site." (PMID 37981704, 2023). "We performed these experiments with well-differentiated mouse CD8α+ DCs supported by Flt3L, GM-CSF, SCF, and IL-4 in addition to pulsing by tumor cell lysates, which has turned out to be the most effective approach to produce CD141+ cDC1s." (PMID 36596856, 2023). "IL-33 activates tumor-associated macrophages and dendritic cells by binding to its receptor, ST2, triggering the release of abundant Th2 cytokines, including IL-10, IL-4, and IL-13, which inhibit immune cell responses, hampering tumor clearance and control." (PMID 37686309, 2023). "Tumor cells also promote membrane cholesterol efflux induces IL-4-mediated signaling in macrophages and alters their phenotype to promote tumor invasion and metastasis." (PMID 36816959, 2023). "Overall, the pleiotropy and complexity of IL-4 limits its clinical development as a candidate drug for tumor therapy." (PMID 36936961, 2023). "As a feedback, tumor cells release factors like IL-12, IL-4, hypoxia-inducible factor (HIF)-1α, and HIF-2α to sustain the M2 TAM phenotype." (PMID 38258072, 2023). "Macrophages are classified into tumor-suppressive M1 type (activated by interferon-γ (IFN-γ) stimulation) and tumor-promoting M2 type (activated by IL-4 and IL-13 stimulation) according to the type of stimulation from their environment." (PMID 37370118, 2023). "Th2 cells were known to suppress the development of Th1 cells and the release of IFN-γ, but they also secreted IL-4 and IL-10, which stimulated the growth of tumor cells." (PMID 37274225, 2023). "Among macrophages, M2 macrophages usually play an antiinflammatory role in the tumor microenvironment, with poor antigen presentation ability, low IL-12, and high IL-10, IL-4, and IL-13 secretion characteristics, as well as immunosuppressive effects." (PMID 38813495, 2023). "In this regard, Th2 cells facilitate tumor growth by producing pro-tumor factors such as IL-4, IL-5 and IL-13." (PMID 37773521, 2023). "According to this study, BC patients had significantly lower serum concentrations of IL-4 and significantly higher quantities of the tumor markers, CA15-3, IL-1β, and VEGF." (PMID 36619680, 2023). "Human cancer studies have found IL-4R expression to be elevated in many tumours types such as bladder, lung, breast, liver, and prostate cancer, suggesting that IL-4-signalling can be selectively targeted therapeutically for cancer treatment." (PMID 37455828, 2023). "While Il4r and Igf1 mRNA was expressed in Cd68/Aif1-positive tumour-associated microglia throughout drug-treated PDOX, Il4 expression co-localised with Gfap/S100b-expressing astrocytes exclusive to the interface region of drug-treated PDOX." (PMID 37127652, 2023). "Many stimuli have been reported in the literature, including IFN-γ, GM-CSF, and TNF-α inducing macrophages to M1 polarization for anti-tumor function, and IL-1β, IL-6, IL-10, and IL-4 inducing macrophages to M2 polarization for pro-tumor function." (PMID 37063892, 2023). "In humans, immunotherapy with IL‐2,40, 41 IL‐4,42 granulocyte‐macrophage colony‐stimulating factor, or tumor vaccines often results in peripheral blood eosinophilia." (PMID 37669914, 2023). "Surprisingly, some groups have shown that IL-4 induces tumor clearance by promoting granulocytes infiltration." (PMID 36376448, 2023). "Because IL-4 is implicated in secreting IL-10 and TGFB in the microenvironment due to the activation of STAT6, the M2a phenotype jumps to the tumor-promoting macrophage phenotype M2aM2cM2d hybrid." (PMID 37283734, 2023).
tumor (continued). "Our findings revealed a notable dichotomy in the immune response within the tumor microenvironment post-vaccine administration beyond the unique observation of IL-4 activity." (PMID 38203396, 2023). "IL-4, TGFβ and IL-8 were assessed in low amounts (471 to 820 pg/mg of tumor); CCL2, IL-12, IL-6 and IL-10 in moderate amounts (2825 to 3440 pg/mg of tumor); and IFNγ, TNFα, IL-1β and IL-2 in high amounts (6293 to 13,492 pg/mg of tumor)." (PMID 37526660, 2023). "Previous research has shown that Th2-polarized CD4+ T cells secrete cytokines such as IL-4, -5, -6 and -10, which reduce T cell antitumor activity and increase macrophage pro-tumor activity." (PMID 37225919, 2023). "Elevated levels of IL-4 protect tumor cells from apoptosis and contribute to the establishment and maintenance of Th2-polarized immune responses." (PMID 37444608, 2023). "Th2 cells secrete IL-4 and IL-10 to mediate humoral immune responses, which leads to immune suppression and promotes tumor growth and metastasis." (PMID 38343446, 2023). "IL-4 released by Th2 cells and the production of IL-4, IL-10, or IL-13 by tumor cells polarize macrophages into an M2 phenotype." (PMID 36761751, 2023). "In contrast, M2 macrophages that are activated by IL-13 and IL-4 are often employed as accelerators of tumor progression." (PMID 37346073, 2023). "Stimulation of macrophages with IL-4 in these cultures led to an intensified invasion of tumor cells, as evidenced by basement membrane degradation, increased collagenolytic activity, and elevated levels of MMP-2 and MMP-9." (PMID 37686542, 2023). "In our initial transitional monocytes system that mimic the responses of tumor-associated monocytes/macrophages under IFN-based therapy, we have demonstrated the involvement of IL-4 and IL-6 in mediating the IFN-elicited, unconventional M2 program." (PMID 36726024, 2023). "The miR-195-5p/NOTCH2 axis has been reported to induce EMT in CRC cells, which promoted IL-4 secretion to enhance TAMs polarization, thereby promoting tumor progression." (PMID 36841801, 2023). "An example is that TME can enhance immunosuppressive M2 monocyte-derived macrophages by secreting cytokines such as IL-4, which allows the tumor to grow and progress because monocyte-derived macrophages can account for 50% of the tumor mass." (PMID 36785674, 2023). "Th2 cells are a crucial component of type II immune responses by secreting a wide spectrum of cytokines such as IL-4, IL-5, IL-9 and IL-13, which affect both tumor cells and several types of immune cells." (PMID 36376448, 2023). "The relation between tumour growth and IL‐4 has been reported for numerous types of cancer expressing IL‐4 receptor (IL‐4R) including NPC." (PMID 38117000, 2023). "Cholesterol depletion in macrophages induces IL-4-mediated macrophage activation and polarization through the STAT6-PI3K pathway, and these IL-4-mediated macrophages exerted immunosuppressive functions and promoted tumour progression." (PMID 37491279, 2023). "In contrast, M2 macrophages exhibit pro-tumor activities and produce immunosuppressive cytokines such as IL-4, IL-10, and transforming growth factor-β (TGF-β)." (PMID 37510993, 2023). "Macrophages M1 induced by interferon-gamma and LPS can kill tumour cells and pathogens, whereas macrophages M2 induced by IL-4, IL-10, and IL-13 exhibit anti-inflammatory activity and contribute to tumour invasion and angiogenesis." (PMID 37370746, 2023). "IL-4 released from both tumor cells and M2a further promoted more macrophages to polarize toward M2a, which in turn produced more IL-4, thereby forming a positive feedback loop." (PMID 37108657, 2023). "These cells along with tumor cells can also drive tumor growth and proliferation by secreting tumor facilitating cytokines, growth factors and chemokines including but not limited to IL-4, IL-10 and TGF-β." (PMID 36564524, 2023).
tumor (continued). "Mono-DCs showed a distinct cellular morphology 7 days after BM cell cultures were treated with GM-CSF and IL-4 and pulsed with tumor cell lysates." (PMID 36596856, 2023). "Tumor growth was enhanced by IL-4 plus IL-10-stimulated macrophage CM, and tumor growth was more obvious in cells mixed with CM derived from miR-146b−/− macrophages." (PMID 37402945, 2023). "Regarding tumor-specific responses, Th1 and Th2 cells and their related cytokines, including IFN-γ, TNF-α, and IL-4, are mostly considered anti-tumor elements." (PMID 38137433, 2023). "mregDCs have been reported to interact with tumor-infiltrating Treg cells or to inhibit CD8+ T cell-mediated tumor immunity by IL-4 stimulation." (PMID 36869384, 2023). "IL4, which is released by both tumor cells and M2a macrophages, promotes more macrophages to polarize to the M2a phenotype, resulting in a positive feedback loop." (PMID 38035101, 2023). "RNASE2 has been shown to regulate the production of cytokines (e.g., Interleukin-4 (IL-4) and Interleukin-10 (IL-10)), which can modulate the immune response and promote an immunosuppressive microenvironment, allowing tumor cells to escape immune surveillance." (PMID 37999824, 2023). "As expected, the mixture of IL4-activated macrophages and FaDu cells showed greater tumor size, faster growth rate, and higher weight of mouse tumors than the control group (FaDu cells and M0 macrophages)." (PMID 37325064, 2023). "Further, a co-culture of tumor organoids, tumor associated macrophages and CD4+ T cells even further induced an invasive phenotype that appears dependent on IL-4 signaling." (PMID 37091337, 2023). "To conclude, tumor-released factors along with IL-4/IL-13-mediated cell signaling pathways provide M2a macrophages with the ability to promote tumor progression." (PMID 37108657, 2023). "We demonstrate that AAP/NAC inhibits IL-4/STAT6 signaling, and the resulting M2 polarization, in tumor-associated macrophages." (PMID 37835464, 2023). "Meanwhile, Th2 cells secrete IL-4 and IL-10, which promote tumor growth or metastasis through immunosuppression." (PMID 37077908, 2023). "According to this model, in tumor cells, MVP associates with IRF2 and thereby promotes the secretion of pro-tumoral cytokines such as IL-4." (PMID 38264642, 2023). "Stimulation of M2 TAMs toward switch to an M1 proinflammatory phenotype by treating aged mice with a combination consisting of an IL-2 agonist and anti-CD40 therapy reduced immunosuppressive IL-4 and IL-10 expression and inhibited tumor growth." (PMID 36945046, 2023). "Th2 cells play a pro-tumorigenic role by secreting IL-4, IL-5, and IL-13, which promote tumor growth and metastasis." (PMID 37324186, 2023). "In general, M2 cells acquired in response to IL-4 are oriented toward tissue repair and remodeling, immune regulation, and tumor promotion." (PMID 37039038, 2023). "M2-macrophages (CD163+), on the other hand, are, e.g., activated by interleukin 4 (IL4), dampen inflammatory reactions and promote immunoevasion of tumor cells as well as invasion and angiogenesis." (PMID 37345035, 2023). "A protumorigenic TME is saturated with several supporting tumor growth cytokines like interleukin (IL)-4, IL-6, and IL-10 as well as transforming growth factor (TGF)-β, interferon (IFN)-γ, and chemokines such as chemokine (C-C motif) ligand 2 (CCL2)." (PMID 38033495, 2023). "On the other hand, M2 macrophages induced by IL-4 and IL-13 play a key role in tumor progression and metastasis." (PMID 36693070, 2023). "Although potentially counterintuitive to classical immuno-oncology paradigms, this function of IL-4 enhancing Th1 responses through dendritic cell activity is in line with the observed mechanisms of IL-4 anti-tumor activity in other published literature." (PMID 38203396, 2023). "IL-4, a known inducer of M2 polarization in the tumor microenvironment, was used to facilitate differentiation of monocytes towards tumor-associated phenotype." (PMID 36960065, 2023).